IL23R (interleukin 23 receptor)
Diseases named in the same sentence as IL23R in open-access papers (continued):
Sharing a sentence is not in itself a finding about the gene and the disease.
pulmonary tuberculosis (4 papers, 2015 to 2022). A bacterial infection that affects the lungs and is caused by Mycobacterium tuberculosis. "The SNP rs7518660 (OR = 4.78, 95 % CI 3.14–8.52) and the CNV in IL23R (OR = 2.75, 95 % CI 1.51–4.98) were significantly associated with susceptibility to pulmonary TB." (PMID 26626589, 2015). "In this study, we found the SNP rs7518660 in IL-23R were associated with pulmonary TB in the Chinese Uygurs." (PMID 26626589, 2015). "Our results also revealed a significant association of IL23R SNPs with the severe clinical forms of pulmonary TB in the Chinese Uygur population." (PMID 26626589, 2015). "There was only one study reporting the only SNP (rs11209026) of IL-23R associated with the development of a severe form (extensive lung infiltration) of active pulmonary TB in Tunisians." (PMID 26626589, 2015). "A hospital based one to one matched case–control study was performed to assess the role of single nucleotide polymorphisms (SNPs) and copy number variation (CNV) of IL-23R in susceptibility and clinical features of pulmonary TB in Chinese Uygurs." (PMID 26626589, 2015). "It is important to determine the degree of LD between the CNV of IL-23R and rs7518660 and rs10889677, given that these variants were all associated with susceptibility to pulmonary TB in Chinese Uygurs." (PMID 26626589, 2015). "Our study shows for the first time that SNP and CNV in IL23R were associated with susceptibility, drug resistance and cavity formation of pulmonary TB." (PMID 26626589, 2015). "Our findings indicate that these IL-23R polymorphisms may be considered as risk factors for active pulmonary TB and its severe clinical forms." (PMID 26626589, 2015). "A hospital based one to one matched case–control study was conducted to determine whether the SNPs and CNV of IL23R are associated with susceptibility and clinical forms of pulmonary TB in Chinese Uygurs." (PMID 26626589, 2015). "The result supports our hypothesis that the increase in the copy number of IL23R is associated with pulmonary TB in the Chinese Uygur population." (PMID 26626589, 2015). "Therefore, we propose a hypothesis that the CNV of IL-23R, if present in Chinese Uygurs, may be associated with sputum positive pulmonary TB." (PMID 26626589, 2015). "Another IL23R mutation (p.R381Q) has been reported as a partial LOF variant and associates with pulmonary tuberculosis severity." (PMID 35829840, 2022). "Our study showed for the first time that IL23R SNPs and CNV are associated with susceptibility to pulmonary TB." (PMID 26626589, 2015). "Thirteen SNPs in IL-23R were genotyped by multiplex SNaPshot and a CNV was analyzed using Taqman real-time PCR in 250 pairs of pulmonary TB patients and controls." (PMID 26626589, 2015).
type 1 diabetes (4 papers, 2007 to 2025). "As genes associated with immune-mediated diseases have an increased prior probability of being associated with other immune-mediated diseases, we tested three such genes, IL23R, IRF5 and CD40, for an association with type 1 diabetes." (PMID 18045485, 2007). "Lack of association of IL23R, IRF5 and CD40 with type 1 diabetes helps to delineate pathogenic mechanisms between type 1 diabetes and other immune-mediated diseases, especially when the associations reported for the other diseases are highly likely to be true positive results." (PMID 18045485, 2007).
Allergy (3 papers, 2013 to 2022). An allergy is an immune response or reaction to substances that are usually not harmful. "As AR is a heterogenetic disease, the environment is critical for the disease; further studies including gene-gene and gene-environment interactions in AR are needed to clarify the impact of IL-23R on allergic disease." (PMID 23696856, 2013). "Moreover, no study reports a genetic association between IL-23R and allergy/atopy from a GWAS approach." (PMID 23696856, 2013).
alopecia areata (3 papers, 2020 to 2024). Loss of scalp and body hair involving microscopically inflammatory patchy areas. "IL-23R has been identified to associate with multiple diseases, including alopecia areata (rs10889677) and nephropathy (rs10805303)." (PMID 33324152, 2020). "This systematic review and meta-analysis were done to find the association between rs3118470, rs2275913, rs3212227, and rs10889677 of the IL2RA, IL17A, IL12B, and IL23R genes, respectively, of the interleukin family with alopecia areata." (PMID 38394507, 2024). "Throughout the assessment, 165 articles were not related to Alopecia Areata and IL2RA, IL17A, IL12B IL23R genes, 11 were non-English publications and 5 articles were on animal models." (PMID 38394507, 2024).
colonic disease (3 papers, 2010 to 2012). "When the analyses were performed on the subgroup of patients with pure colonic disease, the IL23R protective allele (A) was also predictive of an earlier surgery (log-rank, p = 0.007)." (PMID 23300620, 2012). "Colonic disease (including rectum) was associated with the risk alleles of IL23R (G) and the chromosome 6q21 locus (T) and with the protective alleles of IRGM (T) and DEFB1 (A)." (PMID 23300620, 2012). "Colonic disease was significantly associated with disease SNP rs7517847 (IL23R) (p<0.05) and colonic and ileal/colonic disease was significantly associated with disease SNP rs125221868 (IBD5) and SLC22A4 & SLC22A4/5 variants (p<0.05)." (PMID 21079743, 2010). "Even stronger statistical significance was observed for ileo-colonic disease in individuals carrying the A allele of rs1343151 or the G allele in rs7517847 of IL-23R." (PMID 21253534, 2010). "Disease SNP rs7517847 (IL23R) was found more often in CD patients with colonic disease (L2±L4) (14% (10/69)) compared to the wildtype form of this SNP in the same phenotype (1% (1/69)) (p = 0.04)." (PMID 21079743, 2010). "After multivariate analysis, only IL23R and DEFB1 remained associated with colonic disease." (PMID 23300620, 2012).
COVID-19 (3 papers, 2021 to 2023). A disease caused by infection with severe acute respiratory syndrome coronavirus 2. "We also found an increased expression of CD63, ITGB2, CD37, CD2 and IL23R markers and the reduction in CXCR4, CD69, CD48, ICAM1 and S100A10 markers in COVID-19-derived NK-T cells compared to controls." (PMID 34944610, 2021). "Similarly, a low IL23R (ENSG00000162594.15) expression level can indicate patients without dysfunctions, corresponding to an enhanced inflammation-induced decrease in the sense of smell or taste in COVID-19." (PMID 36983953, 2023).
esophageal squamous cell carcinoma (3 papers, 2014 to 2024). Esophageal squamous cell carcinoma (ESCC) is a type of esophageal carcinoma (EC) that can affect any part of the esophagus, but is usually located in the upper or middle third. "In this study, we investigated the effect of extracellular IL-23 in IL-23 receptor-positive (IL-23R+) esophageal squamous cell carcinoma (ESCC) and explored the mechanisms underlying this effect." (PMID 30483821, 2019). "Single nucleotide polymorphisms (SNPs) in IL-23R have been frequently studied in several previous case-control cancer studies, but its association with esophageal squamous cell carcinoma (ESCC) in Chinese population has not been investigated." (PMID 24586528, 2014).
fibrosarcoma (3 papers, 2021 to 2023). A malignant mesenchymal fibroblastic neoplasm affecting the soft tissue and bone. "We transfected JAK2-deficient γ2A-fibrosarcoma cells expressing IL-23R and IL-12Rβ1 with various amounts of JAK2-encoding constructs and assessed their response to IL-23." (PMID 37875108, 2023). "Like P1104A, all the missense proteins resulted in impaired responses to IL-23 in TYK2-deficient fibrosarcoma (U1A) cells stably expressing IL-12Rβ1 and IL-23R." (PMID 36094518, 2022). "Both IL-23A and IL-23R deficient mice were found to be resistant to chemical-induced skin papillomas or fibrosarcomas." (PMID 34093846, 2021).
lymph node metastasis (3 papers, 2012 to 2014). "Strong IL23R expression and the translocation of beta-catenin, regulated by the GnRH/GnRHR pathway, were seen in some of the patient samples and correlated with signs of poor prognosis, namely Dukes' staging and the presence of lymph node metastasis." (PMID 22173670, 2012). "Upregulated IL-23R immunoreactivity correlated with Dukes' staging and lymph node metastases." (PMID 22173670, 2012).
oral cancer (3 papers, 2018 to 2025). "The combined expression of VGF and IL23R emerges as a potent predictor of survival in oral carcinoma cases, suggesting potential implications for future therapeutic strategies." (PMID 38528565, 2024). "As lesions advanced to oral cancer, CD4+ cell levels declined in the wildtype mice, while levels in the IL-23R KO mice remained constant." (PMID 29664967, 2018).
Sepsis (3 papers, 2019 to 2022). Sepsis is defined as life-threatening organ dysfunction caused by a dysregulated host response to infection. "Consequently, IL-23R deficiency increased kidney injury and sepsis, while exaggerated inflammation." (PMID 36138043, 2022). "In our study of human sepsis, expression of the signature Th17 transcription factor and of surface IL-23R were reduced in CD4+ lymphocytes of septic patients." (PMID 31658288, 2019). "In CD4+ T cells, IL-23R expression was greater in patients with infection than sepsis (p = 0.005), while in CD8+ T cells, IL-23R expression was greater in patients with sepsis than with patients with infection (p = 0.04) and controls (p<0.001)." (PMID 31658288, 2019). "Thus, the MAIT cells of septic patients failed to express a Th17 phenotype, which is consistent with the depletion of IL-23R expression in MAIT cells in patients with sepsis." (PMID 32560376, 2020). "The discordance between the percentage and absolute counts of MAIT IL-23R+ cells in patients may arise from relative lymphopoenia and redistribution into extra vascular compartments in patients with sepsis." (PMID 32560376, 2020). "However IL23R expression was more frequent in patients with infection (p = 0.001) and sepsis (p = 0.002), compared with healthy controls." (PMID 31658288, 2019). "However IL-23R expression was greater in CM T cells from patients with infection compared with sepsis (p = 0.01) and was greater in EM T cells from patients with sepsis (p = 0.008) and from patients with infection (p = 0.003) compared with healthy controls." (PMID 31658288, 2019). "Furthermore as IL-23R expression was greater in CD3+ and CD3+CD4+ lymphocytes of patients with infection, who did not have multiple organ failure, then an exaggerated Th17 response in circulating lymphocytes does not appear to be the basis of sepsis induced organ failure." (PMID 31658288, 2019).
tuberculosis (3 papers, 2015 to 2023). A chronic, recurrent infection caused by the bacterium Mycobacterium tuberculosis. "Within the Han Chinese population, we observed that the IL23R polymorphism rs1884444 was associated with an increased risk of severe tuberculosis and tuberculous meningitis." (PMID 37464360, 2023). "Only three articles documented the association between IL23R gene polymorphisms and tuberculosis, focusing specifically on Chinese and Tunisian populations." (PMID 37464360, 2023). "While the presence of IL23R gene polymorphisms has been associated with a wide array of diseases, its relationship with tuberculosis remains comparatively limited." (PMID 37464360, 2023). "Considering the crucial role played by IL23 in the immune response against tuberculosis, we aimed to further explore the potential association between IL23R polymorphisms and the susceptibility as well as severity of tuberculosis." (PMID 37464360, 2023). "Fifthly, our study focused solely on the impact of IL23R gene single nucleotide polymorphisms on tuberculosis susceptibility and severity." (PMID 37464360, 2023). "However, it does indicate a potential association between IL23R gene polymorphism and an elevated risk of severe tuberculosis." (PMID 37464360, 2023). "However, it does indicate a potential link between IL23R polymorphism and an increased risk of developing severe tuberculosis." (PMID 37464360, 2023). "Notably, rs1884444 of the IL23R gene exhibited a noteworthy association with the risk of severe tuberculosis in the comparison between severe tuberculosis and mild tuberculosis before and after adjusting for age and sex (ORa: 1.301, 95% CI: 1.030–1.643; Pa=0.027, respectively)." (PMID 37464360, 2023). "The incidence of tuberculosis (TB) remains high among Chinese Uygurs (a long-dwelling ethnic minority in Xinjiang) in China and the variants in IL-23R likely contribute to individual’s diversity in host response during infection." (PMID 26626589, 2015). "Within our study, we did not observe a significant association between the IL23R gene polymorphisms rs1884444, rs7518660, rs7539625 and tuberculosis." (PMID 37464360, 2023). "Consequently, our investigation unveils that IL23R gene polymorphisms do not appear to be associated with tuberculosis susceptibility in the Chinese Han population." (PMID 37464360, 2023). "Despite these limitations, our research has made a significant contribution by revealing that IL23R gene polymorphism may not be associated with tuberculosis susceptibility in the Chinese Han population but may confer an increased risk of severe tuberculosis." (PMID 37464360, 2023). "Therefore, IL-23R, a key member in the IL-23/IL-17 pathway, also may be a potential target molecule for the therapeutic management of tuberculosis." (PMID 26626589, 2015). "We also found anti-tuberculosis therapy [ATT] reduced PD1 expression on CD4+ T cells and restored IL-23R expression and IL-17 production." (PMID 29996789, 2018).
viral infections (3 papers, 2011 to 2023). "IL23R is a key player in the proliferation and survival of Th17 cells, which are critical for host defense against bacterial, fungal and viral infections at mucosal surfaces." (PMID 22022372, 2011). "In summary, both viral infection and IL-23 delivery elevated IL-23R and IL-10 expression, which might prolong the viral persistence of vvDD-IL-23 in the TME and, in turn, lead to more IL-23 expression." (PMID 34093846, 2021).
acute GVHD (2 papers, 2021 to 2025). "Previous work has shown that IL-23R signaling is required by Th17 cells in order to become pathogenic; however, the effect of BET proteins on the IL-17/IL-23 immune axis especially in the context of acute GVHD remained unexplored." (PMID 34722316, 2021). "Furthermore, PLX2853 significantly reduced IL-23R+ and pathogenic CD4+ IFNγ+ IL-17+ double positive T cell infiltration in gastrointestinal tissues in an acute GVHD murine model." (PMID 34722316, 2021). "Additionally, Th17 pathogenicity has been linked to STAT3 signaling through IL23R, prompting investigation into the role of IL-23R in acute GVHD." (PMID 34722316, 2021). "All these factors are also involved in the pathophysiology of acute GVHD through various mechanisms, including regulating inflammation (NOD2), promoting inflammation (IL-17), inducing proliferation and interferon-γ (IL-23R), and amplifying and prolonging immune responses (MIF)." (PMID 41291248, 2025).
adenoma (2 papers, 2012 to 2014). A neoplasm arising from the epithelium. "Our findings underline an increased expression of IL-23p19, IL-23p40 and IL-23R in the normal-adenoma-carcinoma sequence followed by a marked reduction in expression in lymph node metastases." (PMID 25015728, 2014). "Immunohistochemical detection of beta-catenin (linked to the GnRH pathway) and IL-23R expression was performed on a tissue microarray of 43 MSS (including 8 matched adenoma samples) and 14 MSI (matched tumour and normal colon epithelium) patient samples." (PMID 22173670, 2012). "Cytoplasmic/membranous expression of IL-23 (p19 and p40 subunits) and IL-23R, respectively were over-expressed in carcinomas versus adenomas and normal tissues (p<0.0001) but were reduced in lymph node metastases (p<0.0001)." (PMID 25015728, 2014). "NAV3 copy number changes and elevated IL-23R expression (moderate or strong immunostaining), and/or nuclear beta-catenin were present in three of the adenoma samples." (PMID 22173670, 2012). "NAV3 copy number changes are frequent in CRC and in adenomas, and upregulation of IL23R, following NAV3 silencing, strongly correlates with Dukes’ staging and lymph node metastases." (PMID 22173670, 2012). "For 11 MSS-type CRC patients, it was possible to compare the IL-23R, beta-catenin, and NAV3 FISH results in matched adenoma and tumour samples." (PMID 22173670, 2012). "Elevated IL-23R expression alone was present in two additional adenomas (data not shown)." (PMID 22173670, 2012). "Because of the small number of adenoma samples in these surgical resections, it was not possible to assess correlation between the NAV3 copy number changes, IL-23R and beta-catenin expression, biological behaviour, and prognostic features of the disease." (PMID 22173670, 2012).
allergic rhinitis (2 papers, 2013 to 2017). Inflammation of the nasal mucous membranes caused by an IgE-mediated response to external allergens. "Our intention was to establish an association between polymorphisms in the IL-23R gene and allergic rhinitis (AR) in the Chinese Han population." (PMID 23696856, 2013).
anterior uveitis (2 papers, 2013 to 2025). Inflammation of the iris and anterior chamber of the eye. "In conclusion, our data do not support a relevant role of IL23R and STAT4 polymorphisms in the genetic susceptibility to develop non-anterior uveitis." (PMID 24312163, 2013).
aspergillosis (2 papers, 2021 to 2025). Aspergillosis is an infection, growth, or allergic response caused by the Aspergillus fungus. "We show that eosinophils express RORγt and IL-23R in acute and allergic models of pulmonary aspergillosis." (PMID 34464425, 2021). "With the allergic model of aspergillosis, approximately one third of the lung eosinophils stained positive for IL-23R by flow cytometry." (PMID 34464425, 2021). "We examined the mechanistic basis for eosinophil IL-17 production in pulmonary aspergillosis, focusing on the roles of RORγt, IL-23 and IL-23R." (PMID 34464425, 2021). "Thus, in allergic and acute models of pulmonary aspergillosis, lung eosinophils express IL-17, RORγt and IL-23R." (PMID 34464425, 2021).
Barrett’s esophagus (2 papers, 2024 to 2026). Esophageal lesion lined with columnar metaplastic epithelium which is flat or villiform. "The hypomethylation and overexpression of IL-23R were identified in esophageal adenocarcinoma, indicating that epigenetic regulation of this gene plays a pivotal role in the inflammatory cascade associated with esophageal adenocarcinoma." (PMID 39796684, 2024).
bladder cancer (2 papers, 2021 to 2024). "The IL-23R c.-309C>A allele was identified as a risk factor for bladder cancer." (PMID 39796684, 2024). "The rs10889677 “C” allele was identified as a significant risk factor for bladder cancer, with higher frequencies observed in high-grade and invasive tumors.The subsequent activation of the IL-23/17 inflammatory axis was evidenced by a clear up-regulation of IL-23R." (PMID 39796684, 2024).